GAPDH (glyceraldehyde-3-phosphate dehydrogenase)
Diseases named in the same sentence as GAPDH in open-access papers (continued):
Sharing a sentence is not in itself a finding about the gene and the disease.
diabetes (continued). "4HR administration increased GAPDH activity, which might reduce the oxidative stress of diabetes." (PMID 39596347, 2024). "However, GAPDH is linked with the activation of the AGE-RAGE pathway, which could be the initiating point of diabetes-linked AD pathogenesis." (PMID 35458596, 2022). "It was found that nine active ingredients in sweet potato leaves act on 90 targets related to diabetes, with the main targets for their blood glucose-lowering effects being AKT1, GAPDH, STAT3, TNF, and EGFR." (PMID 41515064, 2026). "In conclusion, we propose that inhibition of β-cell metabolism in diabetes is mediated by accumulation of one or more glycolytic metabolites lying between PFK and GAPDH (i.e., F1,6BP, DHAP or GA3P)." (PMID 36376280, 2022). "CYCA, GAPDH and RPL27 were invariably identified as the most stable genes in our cohort based on their smoking, PVD, diabetes, hypertension, MS and medication status." (PMID 22511915, 2012). "Sub-network from obesity and diabetes datasets indicate the significant roles of SUMO4, GAPDH and EGFR interactions in insulin signalling diabetes progression." (PMID 19997558, 2009). "(b) The second network demonstrates novel interactions between GAPDH and inflammatory and proliferation candidate genes i.e., SUMO4 and EGFR indicating a new link between obesity and diabetes." (PMID 19997558, 2009). "Metabolic dysregulation in diabetes leads to an excessive generation of mitochondrial superoxide inside the endothelial cells of blood vessels, which damages endothelial cells by activation of poly(ADP-ribose) to inhibit GAPDH." (PMID 38702777, 2024). "Control non-diabetes individuals had very little or non-detectable levels of surface RAGE confirmed through densitometry analysis of RAGE/GAPDH." (PMID 36895726, 2023). "The differential expression of PFKM, GAPDH, ACO2, and MDH2 in the urinary exosomes of diabetic patients can serve as potential biomarkers for diabetes monitoring, providing a promising method for noninvasive diabetes diagnosis." (PMID 36187097, 2022). "The underlying mechanisms of ROS through the production of superoxide anions contribute to the pathogenesis of diabetes by upregulating poly(ADPribose) polymerase (PARP) and suppressing the action of glyceraldehyde-3 phosphate dehydrogenase (GAPDH), which constitutes an important glycolytic enzyme." (PMID 36699147, 2021). "In diabetic patients, aerobic oxidative metabolism is reduced, and the expression of aerobic oxidative metabolism-related proteins PFKM, GAPDH, ACO2, and MDH2 in urinary exosomes is reduced, which may become potential biomarkers for monitoring changes in diabetes." (PMID 36187097, 2022). "In contrast, MIF expression was significantly reduced in T2DM-DF compared to ND-DF (58.7 ± 12.3 vs 280.4 ± 126.2% GAPDH; P = 0.0016 for effect of diabetes, two-way ANOVA, n = 4), while TNF-α had no modulatory effect in either (P = 0.7303 for effect of TNF-α, two-way ANOVA, n = 4)." (PMID 33446687, 2021).
ovarian carcinoma (30 papers, 2010 to 2025). A malignant neoplasm originating from the surface ovarian epithelium. "Frequent somatic mutations in the 3′-UTR of GAPDH have been reported to promote the growth of ovarian cancer by sponging miR-125 and thereby affecting the expression of Signal Transducer and Activator of Transcription 3 (STAT3)." (PMID 37082114, 2022). "Based on IPA analysis, 5 proteins, namely PKM, ANXA2, LGAL3, HNRNP1A1, PRDX3 and GAPDH, were found to be associated with the apoptosis signaling pathway in A2780 ovarian cancer cell line." (PMID 35163852, 2022). "Previous studies have reported that under normoxic conditions, the most stably expressed genes in ovarian cancer cells are GAPDH/TBP, while under hypoxic conditions, the most stable candidate housekeeping genes are RPL13A/SDHA." (PMID 38166541, 2024). "Subcellular localization analysis revealed that the expression of GAPDH in the cytoplasm and U6 expression in the nucleus reached nearly 80%, thus confirming that the cytoplasm and nucleus of ovarian cancer cells had been successfully separated." (PMID 37304234, 2023). "In response to an A2780 ovarian cancer cell line treated with 9-methoxycanthine-6-one, it was noted that 3 proteins, namely GAPDH, HNRNPA1 and PKM, suppressed and interfered with the anti-apoptotic protein, BCL-XL." (PMID 35163852, 2022). "We first analysed the expression of the GAPDH housekeeping gene by RT-PCR in the plasma of the ovarian cancer patients." (PMID 25749380, 2015). "In the present study, GAPDH mRNA expression was an independent marker for early tumor progression in a cohort of ovarian cancer patients with poor prognosis." (PMID 24252137, 2013). "In addition, Akt2 kinase suppresses GAPDH-mediated apoptosis in ovarian cancer cells via phosphorylating GAPDH at threonine-235 in rat/threonine-237 in human (Thr-235), thereby decreasing its nuclear translocation." (PMID 40903341, 2025). "From the 12 candidate reference genes we studied, the combination use of ACTB, PPIA, RPLP0, and TBP was identified as a relatively superior normalization strategy, while GAPDH was insufficient for accurate normalization when considering its overexpression in ovarian cancer." (PMID 24776823, 2014). "Down-regulation of GAPDH by siRNA decreases CSF-1 expression in ovarian cancer cells." (PMID 22909061, 2012). "Reverse phase protein array analysis identified significant dysregulation of metabolites (LDHA, GAPDH, and TCA intermediates) in ovarian cancer cells after Grb2 downregulation." (PMID 32754300, 2020). "The results showed that compared with the endogenous control gene GAPDH, SPAG5 expression levels in ovarian cancer tissues and paracancerous tissues were 5.36 ± 4.25 and 1.20 ± 1.21 (P = 0.002), respectively." (PMID 31985007, 2020). "(c) MMP2, EGFR, p-EGFR protein level in ovarian cancer cell under ANGII treatment were measured by Western blot and normalized using GAPDH as a loading control." (PMID 30845964, 2019). "(a) p-AKT and p-ERK protein level in ovarian cancer cell after ANGII treatment were measured by Western blot and normalized using GAPDH as a loading control." (PMID 30845964, 2019). "In a study on ovarian cancer cells, AKT2 inhibits GAPDH nuclear translocation and suppresses GAPDH-induced apoptosis." (PMID 25859407, 2015). "We investigated the prognostic value of the glycolytic enzymes glyceraldehyde 3-phosphate dehydrogenase (GAPDH) and pyruvate kinase type M2 (PKM2), mitochondrial β-F1-ATPase (ATP5B) and the bioenergetic cellular (BEC) index in advanced ovarian cancer." (PMID 24252137, 2013). "Previously, we identified GAPDH protein which binds to ARE and stabilizes CSF-1 mRNA leading to post-transcriptional up-regulation of CSF-1 in ovarian cancer cells." (PMID 22909061, 2012). "Thus, the biological functions of PRMT5 binding to HK2 or GAPDH deserves further exploration, which would hopefully help us to broader implications for proving PRMT5 as a potential target for the treatment of ovarian cancer." (PMID 36999124, 2023).
ovarian carcinoma (continued). "On the other hand, distribution of GAPDH was not different between platin-resistant ovarian cancer cells and their parental control partners." (PMID 34178629, 2021). "In contrast to modifications that cause GAPDH nuclear translocation and lead to apoptosis, the phosphorylation of the enzyme (T237) by protein kinase Bβ was reported, which inhibits both the GAPDH transport and the apoptosis-promoting activity in OVCAR-3 ovarian cancer cells." (PMID 32370188, 2020). "Although GAPDH has been considered as a housekeeping gene appropriate for use as mRNA and protein loading control in experimental settings, its expression in ovarian cancer is not consistent, with 50% of tumor specimens showing no GAPDH expression." (PMID 29991493, 2018). "Here we found that autoreactivity of the 3′-UTR of GAPDH is highly associated with the diagnosis of invasive BC and we speculate that, similarly to the findings in ovarian cancer, changes in the 3′-UTR responsible for autoreactivity may disturb the binding of a miRNA to the 3′-UTR of the GAPDH mRNA." (PMID 37082114, 2022). "While total levels of histone H3 are similar at both RGS10 and GAPDH promoters in chemosensitive and chemoresistant cells, levels of acetylated histone H3 are significantly lower at RGS10 promoters in the chemoresistant C13 ovarian cancer cells as compared to chemosensitive OV2008 cells." (PMID 24475290, 2014). "Also, our results demonstrate that GAPDH should not be used as reference RNA in ovarian cancer." (PMID 24252137, 2013). "(b) p-AKT and p-ERK protein level in ovarian cancer cell under ANGII with/without losartan treatment were measured by Western blot and normalized using GAPDH as a control." (PMID 30845964, 2019). "CD133 expression was examined in ovarian cancer cell lines (OVCAR-8 and IGROV-1) and Ishikawa cells and normalized to GAPDH expression." (PMID 23067401, 2012).
pancreatic cancer (30 papers, 2007 to 2026). "Expression of PRMT3 is upregulated in pancreatic cancer and mediates metabolic reprogramming and cell proliferation by causing R248 methylation of GAPDH." (PMID 41154773, 2025). "The expression of CCNA2, CCNB1, CDC6 and GAPDH have all been implicated in various cancers, including lung, ovarian and pancreatic cancer." (PMID 32899298, 2020). "Nuclear GAPDH positivity was functionally associated to cancer cell death in vitro and in vivo model of pancreatic cancer." (PMID 31027346, 2019). "In addition, fifteen of the proteins have been specifically linked to pancreatic cancer, including cathepsin D, glyceraldehyde-3-phosphate dehydrogenase, intercellular adhesion molecule 1, mesothelin, and tissue factor." (PMID 25987888, 2015). "A recent report showed that PRMT3-mediated methylation of glyceraldehyde-3-phosphate dehydrogenase (GAPDH) at R248 enhances its catalytic activity, thus increasing glycolysis in pancreatic cancer cells." (PMID 40050608, 2025). "PRMT3 has been shown to regulate metabolic reprogramming in pancreatic cancers by methylating glycolytic pathway components such as GAPDH and ABCG2 to reprogram cellular metabolism to promote tumor progression." (PMID 36351894, 2022). "In pancreatic cancer cells, our group found a strong increase in GAPDH nuclear translocation due to oxidation of the enzyme by increased ROS after combined treatment with genipin and everolimus drugs." (PMID 31027346, 2019). "Upregulation of GAPDH has also been reported in several malignancies including ovarian, thyroid, hepatocellular and pancreatic cancers." (PMID 21347333, 2011). "Same conclusion was reported for breast, prostate and pancreatic cancers where transcript levels of GAPDH were found elevated." (PMID 20507635, 2010). "However, in hepatocellular carcinoma (HCC) and pancreatic cancer, it exhibits tumor-suppressive properties, such as inhibiting metabolic reprogramming through the methylation of GAPDH." (PMID 41154773, 2025). "Similarly, AXP-3019, a 3-bromo-isoxazoline derivative, inhibits the proliferation of pancreatic cancer cells by targeting and inhibiting GAPDH." (PMID 39199428, 2024). "We also aimed to test whether pancreatic cancer stem cells (CSCs) may have a differential response to GAPDH inhibition with 3-bromo-isoxazoline derivatives as compared to the parental PDAC cells from which they were derived." (PMID 35804925, 2022). "The overall results support the assumption that selective inhibition of the glycolytic pathway, by targeting GAPDH, is an effective therapy for pancreatic cancer and that 3-bromo-isoxazoline derivatives represent a new class of anti-cancer compounds targeting glycolysis." (PMID 35804925, 2022). "For instance, we discovered that the combined treatment with target drugs, i.e., genipin and everolimus, which are inhibitors of UCP2 and mTOR, respectively, promotes GAPDH nuclear translocation stimulating the formation of autophagic vesicles and pancreas cancer cell death." (PMID 31027346, 2019). "To determine whether the hENT1 × dCK/RRM1 × RRM2 ratio correlated with gemcitabine sensitivity, we examined the relative mRNA expression of hENT1, dCK, RRM1, and RRM2 to GAPDH in eight human pancreatic cancer cell lines." (PMID 17224927, 2007). "Similar to the characterisation of EVs from human pancreatic cancer cell lines, Alix, TSG101 and CD9 were detected whereas calreticulin and GAPDH were undetected in the P100 fractions from KPC and TPAC cells after ultracentrifugation." (PMID 39863771, 2025).
pancreatic cancer (continued). "Besides predicting early recurrence, the panel containing serum exosomal miR-1299, GAPDH (mRNA), circulating mutant KRAS allele fraction, and CA199 levels could effectively predict occult distant metastasis of pancreatic cancer, which was significantly better than imaging alone." (PMID 39054529, 2024). "Ectopic expression of the R248 mutant in human L3.6pl pancreatic cancer cells, which express abundant endogenous PRMT3, also decreased the total GAPDH activity in cells." (PMID 31324208, 2019). "The results showed that GAPDH, Bcl-2 and IGFBP6 were amplified from the positive contrasting template, which confirmed the presence of GAPDH, Bcl-2 and IGFBP6 genes in the total chromatin fraction of pancreatic cancer cells." (PMID 19736394, 2009). "Interestingly, and in line with previous observations carried out in pancreatic cancer cells, we also showed that the CB2 receptor inhibitors dampened the BCP-dependent stimulation of GAPDH activities and downstream enzymes enolase and PK." (PMID 33809114, 2021). "Because GAPDH is an important effector for PRMT3 to reprogram cellular metabolism, we hypothesized that PRMT3-overexpressing pancreatic cancer cells may be addicted to GAPDH for proliferation." (PMID 31324208, 2019). "Moreover, we identified a total of 293 PRMT3-interacting proteins in pancreatic cancer cells and found that PRMT3 methylated GAPDH at arginine 248 to promote glycolysis and mitochondrial respiration simultaneously in cancer cells." (PMID 31324208, 2019). "In pancreatic cancer ACEA induced ROS-mediated autophagy via activation of AMPK, inhibition of energetic metabolism; it decreased Glyceraldehyde 3-phosphate dehydrogenase (GAPDH) and Pyruvate Kinase M2 (PMK2) expression and enhanced the anticancer potential of gemcitabine." (PMID 34943903, 2021). "Our results suggest that PRMT3 mediates metabolic reprogramming and cellular proliferation through methylating R248 of GAPDH, and double blockade of GAPDH and mitochondrial respiration could be a novel strategy for the treatment of PRMT3-overexpressing pancreatic cancer." (PMID 31324208, 2019). "Western blot data showed that the values of p-JNK/JNK and JNK/GAPDH were significantly higher in rhoifolin-treated PANC-1 and ASPC-1 cells than that in the control group, indicating that rhoifolin could induce the JNK pathway in the apoptosis of pancreatic cancer cells." (PMID 35383226, 2022). "In this study, we show that PRMT3-mediated R248 methylation of GAPDH is critical for metabolic reprogramming and cellular proliferation, and double blockade of glycolysis and mitochondrial respiration could be a novel strategy for the treatment of PRMT3-overexpressing pancreatic cancer." (PMID 31324208, 2019).
hepatocellular carcinoma (28 papers, 2007 to 2025). A malignant tumor that arises from hepatocytes. "In an in vivo murine cancer model studied by Northern blot analysis, all three HKGs, i.e., ACTB, PPIA, and GAPDH, were found to be significantly upregulated in hepatoma cells compared to adjacent normal liver tissue." (PMID 40943534, 2025). "In hepatocellular carcinoma patients, the R234 site of GAPDH is in a low methylation state, with CARM1 levels positively correlating with the methylation degree at R234." (PMID 39964832, 2025). "This discovery suggests that CARM1‐mediated methylation of GAPDH is a crucial regulatory mechanism in the glucose metabolism of hepatocellular carcinoma." (PMID 39964832, 2025). "AT-1R mRNA and GAPDH mRNA were expressed in all hepatocellular carcinoma tissues and normal liver tissues." (PMID 24396398, 2014). "For example, GAPDH showed stable expression and could be used as a reference gene for gene expression studies in human leukocytes, reticulocytes, hepatocellular carcinoma, prostate cancer and heart tissue." (PMID 20380724, 2010). "They focused on CARM1, which methylates GAPDH at R234 and inhibits its catalytic function in hepatocellular carcinoma (HCC)." (PMID 32549751, 2020). "In hepatocellular carcinoma cells, CARM1-mediated GAPDH methylation is a key regulatory mechanism of glucose metabolism, retarding the proliferative capacity of cancer cells by regulating the metabolic reprogramming of tumor cells." (PMID 41154773, 2025). "These analyses suggest that EFTUD2, GAPDH, NOP56, and PA2G4 were potential biomarkers for the diagnosis and prognosis of hepatocellular carcinoma." (PMID 34257558, 2021). "Therefore, GAPDH, eIF4E and DNA polymerase α might be suitable targets for simultaneous inhibition to restrain growth of hepatocellular carcinoma cells by interrupting of energy supply, protein synthesis and DNA replication and ultimately triggering cell death." (PMID 25691059, 2015). "Some qPCR studies on hepatocellular carcinoma (HCC) used GAPDH or ACTB for normalization." (PMID 17640361, 2007). "For example, GAPDH regulation has not been found in Hep-1-6 mouse hepatoma, Hep-3-B and HepG2 human hepatocellular carcinoma, A-549 human adenocarcinoma, and HT-29 and HCT-116 colon cancer cell lines." (PMID 32252351, 2020). "The 3-BrPA-induced -severe- reduction of GAPDH, but not HK2, cellular contents in T24 (and T24-X) can be associated with drug’s potency to strongly inhibit GAPDH, but not HK2, glycolytic activity in hepatocellular carcinoma cells." (PMID 26198749, 2015). "Moreover, in hepatocellular carcinoma and osteoblasts, CARM1 induces complex metabolic reprogramming by methylating targets including Malate Dehydrogenase 1 (MDH1), Glyceraldehyde-3-Phosphate Dehydrogenase (GAPDH), and Protein Phosphatase 1 Catalytic Subunit Alpha (PPP1CA)." (PMID 41488004, 2025). "created a novel Hepatocellular Carcinoma prediction model that integrates 7 GlnMgs, including SLC1A5, GAPDH, SLC38A1, SLC38A7, FTCD, MTHFS, and GOT2 might be utilized to predict prognosis in HCC." (PMID 37377916, 2023).